IMPDH2 (inosine monophosphate dehydrogenase 2)
Diseases named in the same sentence as IMPDH2 in open-access papers (continued):
Sharing a sentence is not in itself a finding about the gene and the disease.
leukemia (6 papers, 2023 to 2025). A malignant (clonal) hematologic disorder, involving hematopoietic stem cells and characterized by the presence of primitive or atypical myeloid or lymphoid cells in the bone marrow and the blood. "For example, the IMPDH2 inhibitor has been shown to be an effective treatment for MLL-fusion leukemia." (PMID 40426895, 2025). "We then assessed the role of IMPDH1 and IMPDH2 in MLL‐fusion leukemias using the CRISPR/Cas9 system." (PMID 36453131, 2023). "Likewise, leukemia and multiple myeloma cell lines mainly express IMPDH2 with little IMPDH1." (PMID 41154443, 2025). "The expression of IMPDH2 and multiple nucleolar proteins was higher in MLLGA and correlated with the response to IMPDH inhibition in KMT2A rearranged leukaemia, suggesting a role of the nucleolar activity in sensitivity to treatment." (PMID 36843114, 2023).
triple-negative breast carcinoma (6 papers, 2022 to 2025). An invasive breast carcinoma which is negative for expression of estrogen receptor (ER), progesterone receptor (PR), and human epidermal growth factor receptor 2 (HER2). "Shikonin, a selective IMPDH2 inhibitor, was reported to suppress the growth of triple-negative breast cancer cell line MDA-MB-231." (PMID 35416106, 2022). "Importantly, previous studies have reported a significant increase in apoptosis following IMPDH2 inhibition in cell lines derived from triple-negative breast cancer and diffuse large B-cell lymphoma." (PMID 39085725, 2024). "Likewise, shikonin inhibits the development of triple-negative breast cancer by inhibiting IMPDH2 expression." (PMID 39188951, 2024).
breast carcinoma (5 papers, 2015 to 2026). "The presence of SP1 together with IL2 signaling regulators, IGFBP2, IMPDH2 and HTT in separate subnetworks that excludes RAC signaling component might indicate the presence of at least two non-redundant mechanisms in P-inter breast cancers that may determine patient outcomes." (PMID 26257336, 2015).
COVID-19 (5 papers, 2020 to 2025). A disease caused by infection with severe acute respiratory syndrome coronavirus 2. "ANKRD9 is a gene involved in a variety of cellular processes, including the degradation of IMPDH2, and IMPDH2 is involved in the viral response pathway and considered a therapeutic target for COVID-19 treatment." (PMID 38495196, 2024). "The link between ANKRD9 and IMPDH2 is striking given that IMPDHs are considered therapeutic targets for COVID-19." (PMID 35798818, 2022). "The link between ANKRD9 and IMPDH2 is compelling in light of the role of IMPDHs as therapeutic targets for COVID-19." (PMID 35798818, 2022).
glioma (4 papers, 2022 to 2025). A benign or malignant brain and spinal cord tumor that arises from glial cells (astrocytes, oligodendrocytes, ependymal cells). "Higher IMPDH1 expression is linked to poorer prognosis in renal cancer, liver cancer, urothelial cancer, glioma, and cervical cancer, while high IMPDH2 levels associate with poor prognosis in liver cancer." (PMID 40186514, 2025). "For instance, four cohorts of glioma patients showed that higher IMPDH2 expression was positively correlated with the risk of malignancy, a poor prognosis, and even chemoresistance." (PMID 37409959, 2023). "IMPDH2 was found to be overexpressed in high-grade gliomas, and inhibition of IMPDH2 activated IRBC, resulting in glioma cell growth arrest." (PMID 35565259, 2022). "As an example, besides IMPDH2 (previously discussed), impaired de novo biogenesis of pyrimidines through inhibition of DHODH (dihydroorotate dehydrogenase) downregulates rRNA synthesis and triggers IRBC in glioma cells." (PMID 35565259, 2022).
lung cancer (4 papers, 2023 to 2024). A malignant neoplasm involving the lung. "Here, we present evidence that B7-H3 is associated with one of the key rate-limiting metabolic enzymes IMPDH2, and the localisation of this complex is altered in human lung cancer cells that express high levels of B7-H3." (PMID 37444640, 2023). "The expression between primary lung carcinoma and its BM-paired sample (n = 23) varied (decreased, maintained, or increased) depending on the patient (paired t test p = 0.317 and 0.447, respectively, for IMPDH1 and IMPDH2)." (PMID 39366383, 2024).
multiple myeloma (4 papers, 2018 to 2026). "For instance, multiple myeloma cells express higher levels of IMPDH2, and MMF use results in a positive clinical response." (PMID 37409959, 2023). "For instance, increased IMPDH2 expression was observed in human melanoma cell lines, human ovarian tumors, human leukemic cell lines and multiple myeloma cells." (PMID 30518405, 2018). "Furthermore, inhibition of IMPDH2 activity increased sensitivity to methotrexate in HT29 human colon cancer cells, and induced growth arrest of human multiple myeloma cells." (PMID 30518405, 2018).
cervical cancer (3 papers, 2015 to 2025). A primary or metastatic malignant neoplasm involving the cervix. "Consistently, IMPDH1, but not IMPDH2, was found to be an indicator of poor prognosis in our cohort, suggesting that cytoophidia may be a therapeutic target in cervical cancer." (PMID 36816023, 2023).
colon cancer (3 papers, 2017 to 2024). "In addition, researchers found the sensitivity of HT29 human colon cancer cells were significantly increased towards chemotherapy by down-regulating the IMPDH2 gene expression in the resistant cells." (PMID 28389646, 2017). "Consistently, comparison of IMPDH2 mRNA expression in human colon tumours and paired normal colon mucosa samples from the Gene Expression Omnibus (GEO) databases (GSE10950) demonstrated the upregulation of IMPDH2 in cancer." (PMID 38310229, 2024).
psoriasis (3 papers, 2020 to 2025). An autoimmune condition characterized by red, well-delineated plaques with silvery scales that are usually on the extensor surfaces and scalp. "MPA exhibits efficacy in psoriasis through preferential inhibition of the type II isoform of inosine monophosphate dehydrogenase (IMPDH2), a key enzyme in the synthesis of purines." (PMID 40142133, 2025). "There was a positive association between the Psoriasis Area and Severity Index (PASI) score and three proteins (TFRC, IMPDH2, KRT2)." (PMID 36483564, 2022). "PRM validation of 9 proteins that were highly expressed in the drug metabolism pathway further confirmed significant upregulation of MPO (17.05), TYMP (2.44), and IMPDH2 (1.78) in psoriasis lesions." (PMID 32817748, 2020).
Alzheimer disease (2 papers, 2021 to 2024). A progressive, neurodegenerative disease characterized by loss of function and death of nerve cells in several areas of the brain leading to loss of cognitive function such as memory and language. "Remarkably, upregulation of IMPDH2, which often triggers its polymerization, is reported in Alzheimer’s diseases postmortem tissue and mouse models, suggesting a broader implication of IMPDH2 polymerization in neurodegeneration." (PMID 39075237, 2024). "Notably, an animal model study of hippocampal proteomics analysis showed that the IMPDH2 protein was significantly altered in an Alzheimer’s disease 5XFAD mouse model." (PMID 34827437, 2021).
B-cell lymphoma (2 papers, 2021 to 2025). "IMPDH1 and IMPDH2 are highly expressed in proliferative lymphoid malignancies, including T- and B-cell lymphomas." (PMID 41154443, 2025). "This study shows that mycophenolic acid (MPA) induces the expression of catalytically inactive IMPDH2 and promotes filament formation in T-cell and B-cell lymphomas." (PMID 41154443, 2025). "Two of these genes, IMPDH2 and SAMSN1 are highly expressed genes in our list of biomarker candidates for B-cell lymphoma." (PMID 34570764, 2021).
bladder cancer (2 papers, 2023 to 2025). "Based on our findings we confirmed that IMPDH1 and IMPDH2 are target genes of UCA1 controlling purine metabolism in bladder cancer." (PMID 37215997, 2023). "In other words, UCA1 affects the expression of pre-rRNA and GTPase activity by regulating IMPDH1 and IMPDH2, thus promoting the malignant behavior of bladder cancer." (PMID 37215997, 2023). "To examine the effect of IMPDH1 and IMPDH2 on bladder cancer cell's malignant behavior, we constructed stable cell lines knockdown IMPDH1/2 in 5637 cells and UMUC2 cells." (PMID 37215997, 2023). "The overexpression of IMPDH2 in bladder cancer tissues is highly correlated with patient's poor prognosis." (PMID 37215997, 2023). "Furthermore, the long non-coding RNA (lncRNA) UCA1 facilitates bladder cancer progression by recruiting the transcription factor TWIST1 to the promoter regions of IMPDH1 and IMPDH2, thereby upregulating their expression." (PMID 41179679, 2025). "MPA and MMF inhibited the activity of IMPDH in bladder cancer cells; however, our study found that with the use of MPA and MMF, the expression of IMPDH1 and IMPDH2 proteins in bladder cancer cells increased, partially resisting the adverse effects of the decreased activity of IMPDH on tumor cells." (PMID 37215997, 2023).
diffuse large B-cell lymphoma (2 papers, 2024 to 2025). "In hematological cancers like mantle cell lymphoma (MCL), diffuse large B-cell lymphoma (DLBCL), chronic lymphocytic leukemia (CLL), acute myeloid leukemia (AML), and anaplastic large cell lymphoma (ALCL), IMPDH2 levels are significantly higher than IMPDH1." (PMID 41154443, 2025).
hepatocellular carcinoma (2 papers, 2017 to 2022). A malignant tumor that arises from hepatocytes. "The lncRNA SNHG1, which is involved in several cancers, such as hepatocellular carcinoma and non-small cell lung cancer, was functionally associated with PAICS and IMPDH2 in this subpathway." (PMID 28152521, 2017). "Although high expression of IMPDH2 has been reported in various cancers, the roles of IMPDH1 in hepatocellular carcinoma (HCC) are largely unknown." (PMID 35403278, 2022).
lung adenocarcinoma (2 papers, 2022 to 2023). A carcinoma that arises from the lung and is characterized by the presence of malignant glandular epithelial cells. "FANCI is a key protein in DNA repair and ribosome biogenesis and cooperates with IMPDH2 to promote cell proliferation of (lung adenocarcinoma) LUAD." (PMID 35846349, 2022). "Images of human lung slices further demonstrated the presence of IMPDH2 and B7-H3 in RR structures in both non-AT2 and AT2 lung epithelial cells, whereby the latter of which are the best characterised origin of lung adenocarcinoma." (PMID 37444640, 2023).
lymphoma (2 papers, 2023 to 2024). A malignant (clonal) proliferation of B- lymphocytes or T- lymphocytes which involves the lymph nodes, bone marrow and/or extranodal sites. "Taken together, our results suggest that MYC is predominantly responsible for IMPDH2 gene induction and that EBNA2 plays an indirect or supplemental role, at least in cases of EBV primary infections and lymphoma cell lines." (PMID 37409959, 2023). "The expression levels of IMPDH2 in primary lymphocytes and lymphomas are strongly correlated with those of MYC but not EBNA2." (PMID 37409959, 2023).
nasopharyngeal carcinoma (2 papers, 2010 to 2017). A carcinoma arising from the nasopharyngeal epithelium. "However, little is known about IMPDH2 expression and its clinical significance in nasopharyngeal carcinoma (NPC)." (PMID 28389646, 2017).
renal carcinoma (2 papers, 2021 to 2025). A carcinoma arising from the epithelium of the renal parenchyma or the renal pelvis. "Interestingly, one study demonstrated GTP-biosynthetic enzymes, including IMPDH1 and IMPDH2, were highly accumulated at the leading edge of renal carcinoma cells." (PMID 34035425, 2021).
and T-cell lymphoma (1 paper, 2021). "In dividing cells extreme up-regulation of IMPDH2 can lead to cell proliferation and malignancy in B- and T-cell lymphoma as well as other cancers." (PMID 34570764, 2021).
anorexia nervosa (1 paper, 2025). A disorder most often seen in adolescent females characterized by a refusal to maintain a minimally normal body weight, an intense fear of gaining weight, a disturbance in body image, and, in postmenarcheal females, the development of amenorrhea. "In addition, SMG9 in AD, TCTA in anorexia nervosa, RHOA and IMPDH2 in intelligence, CRHR1 in PD, and PHF7 in schizophrenia are all reported to be conserved among a wide range of species, although their relations with the corresponding traits remain to be explored." (PMID 39905509, 2025).
asthma (1 paper, 2023). "Our laboratory previously published an autoantibody panel which consisted of Annexin 1, Annexin 2, IMPDH2, HSP70, PGAM1, and Ubiquillin 1, and properly classified 93% within five clinically distinct groups: osteoarthritis, “cancer-free” control, asthma/COPD, benign nodule, and NSCLC." (PMID 37190187, 2023).
bladder urothelial carcinoma (1 paper, 2023). "In human bladder urothelial carcinoma (BLCA) tissues, the proteins expression of IMPDH1, IMPDH2, and TWIST1 was up-regulated." (PMID 37215997, 2023).
brain tumor (1 paper, 2025). "Moreover, genes previously identified in our BMIC gene signature as well as associated with brain tumor initiating cells (IMPDH2, PROM1) were also detected, independently confirming our previous findings and further supporting the validity of our strategy." (PMID 40601773, 2025).
cognitive decline (1 paper, 2021). "These mice demonstrated a link between cognitive decline and impaired learning with altered IMPDH2 protein function and expression." (PMID 34827437, 2021).
colon adenocarcinoma (1 paper, 2024). "The results revealed that the mRNA expression of IMPDH2 was significantly elevated relative to that in normal tissues in several common cancer types, including colon adenocarcinoma (COAD) and rectum adenocarcinoma (READ)." (PMID 38310229, 2024).
dystonia disorders (1 paper, 2021). "IMPDH2 is the first and rate-limiting enzyme in the de novo biosynthesis of guanine nucleotides, a dopamine synthetic pathway previously linked to childhood or adolescence-onset dystonia disorders." (PMID 34305140, 2021).
esophageal cancer (1 paper, 2022). A primary or metastatic malignant neoplasm involving the esophagus. "The recombinant fusion protein Fv-LDP-D3 suppressed IMPDH2, which provides a new idea for the development of esophageal cancer drugs." (PMID 35416106, 2022). "However, rarely studies have been reported on IMPDH2 as a potential therapeutic target for esophageal cancer." (PMID 35416106, 2022). "Of course, it should be noted that targeting inhibition of p-EGFR/IMPDH2 signaling may be able to improve esophageal cancer treatment efficacy, and the question as to whether there is a relationship between IMPDH2 and EGFR signaling requires in-depth experimental exploration." (PMID 35416106, 2022).
Ewing sarcoma (1 paper, 2026). A small round cell tumor that lacks morphologic, immunohistochemical, and electron microscopic evidence of neuroectodermal differentiation. "Western blot analysis confirmed high expression of the IMPDH2 protein expression in three representative Ewing's sarcoma cell lines (RD-ES, SK-ES-1, and TC71), and provided additional validation of the TCGA data at the protein level." (PMID 41522344, 2026). "To confirm the presence of IMPDH2 protein in Ewing's sarcoma, we conducted western blot analysis of three representative Ewing's sarcoma cell lines (RD-ES, SK-ES-1, and TC71)." (PMID 41522344, 2026). "To evaluate the effect of the IMPDH2 inhibitor AVN944 on proliferation of TC71 Ewing's sarcoma cells, we treated them with 1 μM AVN944 and monitored morphological changes over 5 days." (PMID 41522344, 2026). "This study evaluates the efficacy of AVN944, an IMPDH2 inhibitor, as a treatment for Ewing's sarcoma, a challenging malignancy in pediatric and young adult patients." (PMID 41522344, 2026). "We focused on expression of IMPDH2 in Ewing's sarcoma cell lines, and explored its potential as a therapeutic target in Ewing's sarcoma." (PMID 41522344, 2026). "Thus, AVN944 displays potent anti-tumor activity against Ewing's sarcoma cells both in vitro and in vivo by inhibiting IMPDH2." (PMID 41522344, 2026). "Importantly, the present study provides comprehensive evidence that the IMPDH2 inhibitor AVN944 exerts potent anti-proliferative and anti-clonogenic effects against two Ewing's sarcoma cell lines, TC71 and SK-ES-1." (PMID 41522344, 2026). "To confirm that the inhibitory effects of AVN944 are attributable to blockade of IMPDH2 activity rather than compound-specific actions, we next tested the effects of two structurally and mechanistically distinct IMPDH2 inhibitors, MPA and SA, against Ewing's sarcoma cell lines TC71 and SK-ES-1." (PMID 41522344, 2026).
generalized dystonia (1 paper, 2023). "The phenotype of this syndrome, including variably expressed generalized dystonia, motor disability, and cognitive disability, resembles phenotypes in cases of IMPDH2 variants." (PMID 37414152, 2023).
Hepatitis (1 paper, 2020). Inflammation of the liver. "However, SNPs in IMPDH2 gene encoding the enzyme inosine 5′-monophosphate dehydrogenase type II have been found to affect the response of patients receiving antiviral hepatitis drugs, such as ribavirin, taribavirin, merimepodib, and mycophenolate mofetil." (PMID 32326111, 2020).
hepatoblastoma (1 paper, 2024). Hepatoblastoma (HB) is a malignant hepatic tumor and is the most common pediatric liver cancer. "To delineate the molecular mechanisms underlying the inhibitory effects observed upon IMPDH2 knockdown, we performed RNA sequencing on hepatoblastoma (HB) cell lines with IMPDH2 knockdown." (PMID 39085725, 2024). "In the present study, our analysis of public databases revealed a significant overexpression of IMPDH2 in hepatoblastoma (HB) tissues, particularly in cases associated with metastasis and recurrence of the disease." (PMID 39085725, 2024). "The present study unveiled a significant overexpression of inosine monophosphate dehydrogenase 2 (IMPDH2) in hepatoblastoma (HB) tissues, particularly in association with metastasis and recurrence of the disease." (PMID 39085725, 2024). "However, the precise role of IMPDH2 in the molecular mechanisms underlying hepatoblastoma (HB) remains insufficiently characterized within the current literature." (PMID 39085725, 2024). "To elucidate the biological role of inosine monophosphate dehydrogenase 2 (IMPDH2) in hepatoblastoma (HB) cells, we experimentally downregulated IMPDH2 expression in HB cell lines." (PMID 39085725, 2024).
influenza (1 paper, 2019). An acute viral infection of the respiratory tract, occurring in isolated cases, in epidemics, or in pandemics; it is caused by serologically different strains of viruses (influenzaviruses) designated A, B, and C, has a 3-day incubation period, and usually lasts for 3 to 10 days. "The ribonucleotide synthesis enzyme inosine monophosphate dehydrogenase 2 (IMPDH2), a cellular factor that interacts with the PARP1 and PARP2 DDR proteome network, was also required for influenza NP synthesis." (PMID 31015836, 2019).
inherited dystonia (1 paper, 2021). An instance of dystonic disorder that is caused by an inherited modification of the individual's genome. "Our findings highlight the cell-type-specific importance of metabolic pathways and their directionality and point towards a shared pathophysiological mechanism behind IMPDH2 deficiency and other inherited dystonias." (PMID 34305140, 2021).